ZNF582 (zinc finger protein 582)
Diseases named in the same sentence as ZNF582 in open-access papers (continued):
Sharing a sentence is not in itself a finding about the gene and the disease.
cancer (16 papers, 2012 to 2026). A tumor composed of atypical neoplastic, often pleomorphic cells that invade other tissues. "Subsequently, we validated the most potent markers (ASCL1, LHX8, SST, WDR17, ZIC1 and ZNF582) in a large independent series, confirmed the accuracy (AUC = 0.89) and showed that high methylation levels are associated with progression towards cancer." (PMID 33580586, 2021). "Patients exhibiting high methylation in SOX1, PAX1, and ZNF582 exhibited increased risk of cancer." (PMID 40256126, 2025). "•Elevated ASCL1 and ZNF582 methylation is associated with progression to cancer." (PMID 38160718, 2023). "In particular, a combination of methylation markers ZNF582 and ASCL1 shows the highest accuracy for AIN3+ detection and provides a promising tool to identify HSIL at risk of progression to cancer and in need of treatment." (PMID 40400293, 2025). "The tumor suppressor role of ZNF582 was also observed in anal cancer and esophageal carcinoma, and its methylation seems to have potential as a cancer detection biomarker." (PMID 34359370, 2021). "Published literature on promoter methylation of ADCY8, CDH8, and ZNF582 has expanded recently and hypermethylation of one or more of these loci have been found in cancers of the breast, oropharynx, esophagus, and anus." (PMID 33178175, 2020). "The sensitivities and specificities of PAX1 and ZNF582 methylation for the detection of cancer were 100% and 85.7%, and 78.6% and 100%, respectively." (PMID 28241446, 2017). "The methylation levels of PAX1, SOX1, and ZNF582 showed significant elevation in cancer patients." (PMID 40256126, 2025). "The present study found that ZNF582 is highly methylated in invasive cancer tissues." (PMID 22815913, 2012). "However, its silencing in invasive cancer lesions suggests that ZNF582 may be a tumor suppressor; the expression of which increases in response to oncogenic stress in precancer stages." (PMID 22815913, 2012). "Although the methylation levels of ELMO1, ZNF582 and TFPI2 all showed a significant difference between each cancer type and control subjects, they still showed a preference for a certain cancer type." (PMID 36358701, 2022). "Both methylation of ZNF582 and PAX1 were significantly higher at the cancer sites than at the adjacent normal sites." (PMID 34359370, 2021). "Hypermethylated ZNF582 and PAX1 genes have also been found in mouth rise samples applicable to the detection of oral dysplasia and cancer." (PMID 33178175, 2020). "By other two methylomic methods, we further discovered Zinc finger protein 582 (ZNF582), AJAP1, HS3ST2, and POU4F3 are highly methylated in cancer and precancerous lesions." (PMID 26057869, 2015). "DBC1, ZNF582, and PDE8B demonstrated high methylation levels in more than four cancer pools, and were chosen for further validation in individual samples." (PMID 22815913, 2012). "ZNF582 protein expression increased significantly from normal squamous epithelium to CIS, and then decreased as the cancer cells progressed to invasive and metastatic forms." (PMID 22815913, 2012). "Recent studies revealed that methylated ZNF582 in the promoter was an essential epigenetic mechanism for cancer silence, and it has been demonstrated that hypermethylation occurred in EC tissues; however, the study of methylated ZNF582 in EC plasma has not been reported." (PMID 36358701, 2022).
tumor (8 papers, 2012 to 2024). "Decreased ZNF582 expression is correlated with higher tumor stage and grade, distant metastasis and poor prognosis." (PMID 36966163, 2023). "Previous studies have shown that the expression of ZNF582 and its methylation status can be used as biomarkers for tumor biological diagnosis and prognosis prediction." (PMID 36966163, 2023). "Reduced ZNF582 expression is also closely related to higher tumor stage and grade, distant metastasis and shorter OS and RFS." (PMID 36966163, 2023). "To verify the inhibitory effect of ZNF582 on ccRCC tumor growth and metastasis in vivo, we constructed a mouse orthotopic tumor growth model." (PMID 36966163, 2023). "In order to verify this view, it is necessary to verify the expression of ZNF582 and its methylation status in more tumor types in the near future." (PMID 36966163, 2023). "Taken together, ADCY8, CDH8, and ZNF582 promoter methylation are promising predictive and prognostic biomarkers for multiple tumor types crossing geographic and racial boundaries that undeniably merits further validation." (PMID 33178175, 2020). "The frequency of ZNF582 methylation was 88.2% (165/187) in the tumor samples, which is significantly higher than that (18.8%, 3/16) in the paracancerous samples." (PMID 28241446, 2017). "The methylation rates of PAX1 and ZNF582 in ESCC tumor and paracancerous tissues were 100% and 21.4% (p = 0.006), 85.7% and 0% (p < 0.001), respectively." (PMID 28241446, 2017). "The frequency of ZNF582 methylation in tumor tissues (85.7%, 12/14) is significantly higher than that (0%, 0/14) in paracancerous tissues." (PMID 28241446, 2017). "The DNA methylation levels and frequencies of PAX1 and ZNF582 genes were markedly higher in ESCC tumor tissues compared to those in paracancerous tissues." (PMID 28241446, 2017). "The methylation level of ZNF582 was higher in the tumor samples compared to their paired paracancerous samples in 93.8% (15/16) ESCC patients." (PMID 28241446, 2017). "In the present study, we demonstrated that ZNF582 gene was much more frequently methylated in ESCC tumor tissues compared to non-tumor paracancerous tissues." (PMID 28241446, 2017). "DNA methylation of PAX1 and ZNF582 genes in both tumor and paracancerous tissues was detected successfully using the current analysis." (PMID 28241446, 2017). "Our current study demonstrated for the first time that both the levels and frequencies of PAX1 and ZNF582 methylation were greatly higher in the ESCC tumor tissues compared to non-tumor paracancerous tissues." (PMID 28241446, 2017). "Moreover, lung ex vivo imaging data indicated that ZNF582 overexpression also inhibits the spontaneous lung metastasis of tumor cells." (PMID 36966163, 2023). "Furthermore, after knocking down TJP2 expression based on ZNF582 overexpression, the tumor growth rate is significantly restored." (PMID 36966163, 2023). "Using quantitative methylation-specific PCR (qMSP), we demonstrated for the first time that PAX1 and ZNF582 genes were aberrantly methylated in ESCC tumor tissues compared to the paracancerous normal tissues, and the levels of DNA methylation were significantly associated with tumor progression." (PMID 28241446, 2017). "Paired boxed gene 1 (PAX1) and zinc finger protein 582 (ZNF582) are two tumor suppressor genes." (PMID 28241446, 2017). "The expression of ZNF582 in precancerous lesions in accordance with disease severity in tissue sections may fail to support the role of ZNF582 as a tumor suppressor gene." (PMID 22815913, 2012). "PAX1 and ZNF582 methylation testing has an excellent accuracy, sensitivity and specificity in distinguishing ESCC tumor tissues from non-tumor tissues." (PMID 28241446, 2017). "Promoter methylation of four candidate tumor suppressor genes (adenylate cyclase 8 (ADCY8), cadherin 8, type 2 (CDH8), MGMT, and zinc finger protein 582 (ZNF582)) out of 48 genes screened was quantified by bisulfite-pyrosequencing of genomic DNA." (PMID 27651839, 2016).
tumor (continued). "In tumor tissues, the methylation frequencies of DBC1, PDE8B, and ZNF582 were 13/14 (93%), 4/14 (29%), and 14/14 (100%), respectively." (PMID 22815913, 2012). "The methylation levels of both PAX1 and ZNF582 genes were significantly higher in tumor tissues compared to non-tumor paracancerous tissues." (PMID 28241446, 2017). "However, increased median methylation (~10×) of ADCY8, CDH8, and ZNF582, but not MGMT, was noted in the tumor cohort (N = 257) compared with the three normal samples." (PMID 27651839, 2016).
ZNF582 also shares sentences with these, for which no sentence is quoted: squamous intraepithelial lesions (3 papers); adenocarcinoma (1); anemia (1); cholestasis (1); dysplasia (1); gallbladder cancer (1); hyperplasia (1); liver cancer (1); non-small cell lung carcinoma (1); Pap (1).